PAK2 (p21 (RAC1) activated kinase 2)
Diseases named in the same sentence as PAK2 in open-access papers (continued):
Sharing a sentence is not in itself a finding about the gene and the disease.
cancer (continued). "This review discusses recent discoveries on the functions of PAK2 in the regulation of various types of cancers." (PMID 39769207, 2024). "PAK2 facilitated the angiogenic potential of cancer cells and promotes the epithelial-mesenchymal transition process by activating the TGF-beta signaling pathway." (PMID 38343537, 2024). "Next, we concentrated on analyzing the distinctions in the function of cancer cells with high PAK2 expression compared to those with low PAK2 expression in the signaling communication network." (PMID 38343537, 2024). "Due to its function in regulating cancer cell survival, adhesion, and motility, PAK2 can play an important role in cancer metastasis." (PMID 39769207, 2024). "The number and strength of interactions for high PAK2-expressing cancer cells were significantly higher than those for low PAK2-expressing cancer cells." (PMID 38343537, 2024). "This interaction leaded to reciprocal communication with monocytes/macrophages, mast cells, progenitor cells, and tissue stem cells, while low PAK2-expressing cancer cells had minimal involvement in this signaling pathway." (PMID 38343537, 2024). "While we have only summarized some of the recent research on PAK2′s role in cancer metastasis, the body of research around this gene and its mechanism of action is clearly still at an early stage." (PMID 39769207, 2024). "Across multiple cancers, PAK2 promotes cell proliferation, migration, invasion, and chemoresistance." (PMID 39769207, 2024). "Taken together, these differences illustrate that CMS4 cell lines require PAK2 to orchestrate actin cytoskeleton remodeling for the rapid emergence and turnover of filopodia, which are key structures for cancer cell invasion." (PMID 36869386, 2023). "Phosphorylation of PAK2 on T402 is critical for its activation, and is known to control cell growth and survival in cancer." (PMID 36240067, 2022). "Recent studies have revealed that PAK2 was elevated in many types of cancer and performed oncogenic effects to induce malignant progression in these cancers." (PMID 35333693, 2022). "A study showed that miR-455-3p exhibits anti-cancer effects in colon adenocarcinoma cells by targeting PAK2." (PMID 34778084, 2021). "ZEB1-AS1 inhibits miR-455-3p and dampens the inhibition of PAK2, thereby promoting cancer cell metastasis." (PMID 34778084, 2021). "We showed that miR‐455‐3p plays an anti‐cancer role in COAD by targeting p21‐activated kinases 2 (PAK2)." (PMID 31828845, 2020). "This implies the possible role of PAK2 in the expression of genes involved in the development of major hallmarks of cancer." (PMID 30068946, 2018). "The PAK2 depletion restricted the growth of cancer cells and decreased the chemotherapeutic resistance." (PMID 30068946, 2018). "In this study, miR-4779 inhibited cancer cell growth by inducing apoptosis and cell cycle arrest, and the putative survival factors PAK2 and CCND3 were identified as direct targets of miR-4779." (PMID 29362401, 2018). "Previous studies show that PAK2 promotes cancer cell survival and is overexpressed in various cancers." (PMID 29362401, 2018). "Less is known about the role of PAK2 in cancer despite its pronounced ability to regulate apoptosis." (PMID 28707321, 2017). "That’s partially because many phosphosites who have opposite, antagonistic functions to the activate sites were hypophosphorylated in cancer cells, for example S141 in PAK2 and S43 and S296 in RAF1 in the MAPK pathway." (PMID 28883432, 2017). "PAK1 or PAK2 expression is upregulated in some types of cancer and PAKs were suggested to be a suitable target for anti-cancer therapy as well as for the treatment of airway hyperresponsiveness or in conditions of vascular leak." (PMID 24664099, 2014). "Current data suggest that PAK2 may have an important role in promoting metastasis in various cancers." (PMID 39769207, 2024). "The exact mechanism to activate PAK2 in malignant cancer cells is not well known." (PMID 39769207, 2024).
cancer (continued). "Recent studies have identified mechanisms of PAK2 in promoting metastasis in various cancers." (PMID 39769207, 2024). "More extensive studies are needed to better understand the role of PAK2 in cancer metastasis." (PMID 39769207, 2024). "We specifically presented the analysis results for the EGF signaling pathway, where high PAK2-expressing cancer cells might play a crucial role as key signal transduction nodes, particularly as signal receivers." (PMID 38343537, 2024). "Moreover, in shared signaling communication networks involving both cell types (e.g., COLLAGEN, LAMININ, FN1, MK, and THBS), the contribution of high PAK2-expressing cancer cells was markedly greater than that of low PAK2-expressing cancer cells." (PMID 38343537, 2024). "However, the current research and the development of inhibitors for the clinical applications of PAK1 and PAK2 in the vascular field are relatively limited, and most studies have focused on their role in cancer and neurological diseases." (PMID 39766303, 2024). "This review focuses on the function of PAK2 in the regulation of the metastasis of various cancers." (PMID 39769207, 2024). "In addition, recent studies have shown that PAK2 plays an important role in cancer cell metastasis, indicating PAK2 as a potential therapeutic target." (PMID 39769207, 2024). "In addition, high expression of other key genes like PAK2, LAMB3 and LAMA3 is also associated with malignant tumors." (PMID 37694778, 2024). "A summary of PAK2′s role and mechanism of action in various types of cancer." (PMID 39769207, 2024). "Moreover, a recent report indicated that PAK2 stimulates the activity of the cancer-specific isoform of pyruvate kinase which directs the cell metabolism to aerobic glycolysis." (PMID 37759961, 2023). "Coinciding with this notion, inspection of a publicly available database of large CRISPR-based genetic screens (DEPMAP/PICKLES) unveiled a clear association between sensitivity to loss of PAK2 and loss of its binding partner βPIX (ARHGEF7) across a large panel of pan-cancer cell lines." (PMID 36869386, 2023). "The antiapoptotic effect of PAK2 has been demonstrated in multiple cancer studies." (PMID 35321102, 2022). "PAK2 is modulated by various microRNAs in different cancers." (PMID 35087589, 2022). "PAK 2 has also been reported to promote proliferation and motility of cancer cells." (PMID 36145551, 2022). "MiR‐455‐3p plays an anti‐cancer role in COAD by targeting PAK2." (PMID 31828845, 2020). "PAK2 has been known to play critical roles in many fundamental functions including chromatin remodeling, proliferation, and regulation of cellular apoptosis by mediating proteolytic cleavage during cancer mediated apoptosis." (PMID 32322560, 2020). "These indicated that miR‐455‐3p plays an anti‐cancer role by targeting PAK2 in COAD." (PMID 31828845, 2020). "Next, we examined the role of PAK2 in HNC cell proliferation by depleting PAK2 in three HNC cancer cell lines with shRNA against PAK2 (shPAK2) or against eGFP (shControl) and observed significantly reduced viability in PAK2-depleted cells." (PMID 30068946, 2018). "PAK2 signaling modulates apoptosis and cancers, including breast, hepatocarcinoma, and gastric." (PMID 29270670, 2018). "The miR-107/MCM7/PAK2 pathway may therefore contribute to the development of cancer." (PMID 39769207, 2024). "Thus, PAK2 is a promising target for new drug discovery to prevent cancer metastasis." (PMID 39769207, 2024). "Thus, the novel miR-194-5p/PAK2/XBP1s axis might be the potential prevention/treatment targets for cancer patients receiving DOX treatment." (PMID 35321102, 2022). "Hence, PAK2 downregulation by miR-4779 may inhibit chemo-resistance in various cancers, although further studies are required to confirm the clinical efficacy of miR-4779 mimics." (PMID 29362401, 2018). "This implies that PAK2 could act with RhoH to promote cancer progression." (PMID 29510700, 2018).
cancer (continued). "The selective dependencies on PAK1 and PAK2, as revealed by DepMap CRISPR analysis, position these isoforms as critical components of cancer cell survival in specific contexts." (PMID 39756822, 2025). "Our comprehensive analysis of PAK isoform dependencies, alterations, and their impact on patient survival across a range of cancers highlights the significant and context‐specific roles of PAK1 and PAK2, along with other PAK family members." (PMID 39756822, 2025). "Some studies have accounted for predicted and validated gene targets like GATA2, SKI, NTRK3, PAK2, AR, SP1, and CDK4 that describe their involvement in cancer progression." (PMID 38741808, 2024). "We found that apoptosis-related genes URI1, PAK2, PARP1, CLU, and TIMP3 were significantly upregulated in multiple cell populations of cancer cells." (PMID 37124501, 2023). "Hyperactivation of PAKs also supports cell survival over cell death, and the targeted depletion of PAK1, PAK2, or PAK4 in human cancer cell lines has been shown to compromise fitness and ability to survive in a variety of cancer types." (PMID 36830998, 2023). "In particular STRAP, TRAP1, and PAK2 refer to TGF-β signaling, whose alteration contributes to many diseases, including cancer and fibrosis." (PMID 35051051, 2021). "We have identified a panel of six proteins viz., GOT1, HNRNPA2B1, MAPK1, PAK2, UBE2N, and YWHAB, which contribute to cancer development, and the transition of PCa from androgen dependent to independent stages." (PMID 32322560, 2020). "Collectively, these results showed that PAK2 affects PKM2 expression and suggests an important role of PAK2 in cancer cell energy metabolisms." (PMID 30068946, 2018). "Additionally, the PAK2 expression positively correlates with the higher T-staging, suggesting that the PAK2 could be responsible for the advancement of cancer." (PMID 30068946, 2018). "In summary, we have shown a novel regulatory role of PAK2 in HNC development and a potential framework for HNC cancer therapy by targeting PAK2–c-Myc–PKM2 axis." (PMID 30068946, 2018). "Some signaling communication networks (CD46, HSPG, EGF, CEACAM, PDGF, and EDN) exclusively involved high PAK2-expressing cancer cells, with no participation from low PAK2-expressing cancer cells." (PMID 38343537, 2024). "Nonetheless, targeting PAK2 could, similar to targeting PI3K/AKT activity, represent a future strategy for the treatment of patients with cancers that have acquired CHK1i resistance." (PMID 36240067, 2022). "Similarly, p21-activated kinase 2 (PAK2) and Cyclin D3 (CCND3) were identified as direct targets of miR-4779, a miRNA that inhibits cancer cell growth by inducing apoptosis and cell cycle arrest." (PMID 31450613, 2019). "Additionally, transfection with miR-4779 led to significant reductions in PAK2 and CCND3 protein expression levels in A549, H460, MCF7, and HT-29 cancer cell lines." (PMID 29362401, 2018). "The significance of PAK2 might be explained by its involvement in multiple pathways with the potential to drive ECM remodelling and motility of cancer cells, including those featuring cytoskeletal effector proteins." (PMID 28707321, 2017). "Additional studies will be required to verify whether PAK2 and/or Rho and Rac small GTPases are affected by ABI3 expression in other cancer subtypes and to identify other mediator of cell motility." (PMID 21223585, 2011). "Additionally, another study on ER-positive breast cancer found that in cases of endocrine therapy resistance, reduced CSK leads to enhanced PAK2 activity and subsequent non-estrogen-dependent cancer growth." (PMID 38304232, 2023). "Notably, the current group I PAK inhibitors (PAK‐5339, FRAX597, FRAX1036, and IPA‐3) are not PAK2 selective but have been shown experimentally to have direct antitumour effects as well as ability to overcome chemoresistance in other cancer types." (PMID 37997254, 2024). "PAK1, PAK2, and PAK4 have a higher expression level in most of cancer types, while other PAKs are not." (PMID 33796531, 2021).
infection (6 papers, 2011 to 2025). The state of being infected such as from the introduction of a foreign agent such as serum, vaccine, antigenic substance or organism. "In the case of HIV, following infection, retroviral-encoded proteins directly bind to PAK2 leading to its activation." (PMID 40465712, 2025). "Therefore, we first examined the phenotype of Nef mutants defective for PAK2 association in Jurkat E6.1 clones stably expressing either NFAT-Luc or IL2R-Luc reporter constructs following infection with each Nef variant virus." (PMID 21819585, 2011). "PAK1 and PAK2 affect infection progression (virus, bacteria, and parasitic protists) at various stages, promoting pathogens entry into, replication within, survival, and secretion from host cells." (PMID 33796531, 2021). "Untransfected cells or cells transfected with 10 pmol control siRNA or PAK2 targeting siRNA were infected with VSV-G pseudotyped HIV expressing the indicated Nef and then stimulated 24 h post-infection with α-CD3/CD28 beads for 4 h." (PMID 21819585, 2011). "In addition, we have observed that other proteins involved in promoting or inducing apoptosis, such as DSP, PAK2, and heat shock protein family A (Hsp70) member 8 (HSPA8) proteins, were highly upregulated in rock bream RBCs upon RBIV infection." (PMID 30886611, 2019). "One study demonstrated that siRNA knockdown of PAK2 was not important for infection of HeLa and Jurkat cells." (PMID 21819585, 2011).
cardiovascular diseases (4 papers, 2022 to 2024). "To date, evidence emerging from recent studies has indicated that Pak2 prevents the development of several cardiovascular diseases." (PMID 39899001, 2022). "Involvement of Pak2 in the ER regulatory mechanism suggests that Pak2 can be targeted to develop ER-orientated interventions against cardiovascular disease." (PMID 39899001, 2022). "Therefore, therapeutic strategies modulating Pak2 activation to maintain cardiac ER function are worth exploiting as new means to treat cardiovascular disease." (PMID 39899001, 2022). "However, in Pak2 deleted cardiomyocytes under ER stress, there was a significant induction of RAAS genes, highly implicated in the pathological process of cardiovascular diseases." (PMID 35350536, 2022). "PAK2 is also considered cardioprotective in several cardiovascular diseases." (PMID 35373434, 2022). "Accumulating studies have indicated that PAK1 and PAK2 play important roles in transmitting cellular signals and regulating a range of cellular functions, such as cell proliferation, survival, and apoptosis, making them important therapeutic targets in various cardiovascular disorders." (PMID 39766303, 2024). "Given the role of Pak1/2 in the cardiovascular system, strategies targeting Pak1 and Pak2 could be promising avenues for treating cardiovascular disease by maintaining cellular homeostasis, metabolic function, and enhancing cardiomyocyte adaptation and resilience to stress." (PMID 39899001, 2022).
cardiac disease (2 papers, 2019 to 2022). "The virtues of Pak2 activation provide the rationale for developing novel therapeutic strategies to treat ER dysfunction, a major pathological determinant underlying many forms of heart disease and HF in humans." (PMID 30620686, 2019). "Modulating Pak2 activation is thus proposed as a therapeutic strategy to ameliorate ER dysfunction and aberrant RAAS activation, major pathological determinants underlying many forms of heart disease in humans." (PMID 35350536, 2022). "Moreover, we find a significant increase in Nrf2 with a decrease in Pak2 in human myocardium of dilated heart disease." (PMID 35350536, 2022). "Similarly, using TAC to provoke cardiac disease-mimetic ER stress, we observe a significant reduction in Pak2 phosphorylation and further upregulation of Nrf2 in the hearts of mice after 5 weeks of pressure overload, showing severe cardiac dysfunction and CHOP upregulation." (PMID 35350536, 2022).
myopathy (2 papers, 2019 to 2022). A disease of the muscle in which the muscle fibers do not function properly. "Conditional loss of Pak1 and Pak2 in mice resulted in an age-dependent myopathy with similarity to mice and humans with CHKβ deficiency." (PMID 30791960, 2019). "Loss of both Pak1 and Pak2 in the muscle lineage is required to produce myopathy, and germline mutations in Pak2 result in early embryonic lethality." (PMID 30791960, 2019). "Moreover, those PAK1: PAK2 double KO mice exhibited myopathy with significant alterations in mitochondrial morphology, complicating interpretations." (PMID 35222279, 2022). "We report here that mice lacking Pak1 and Pak2 in the skeletal muscle lineage develop a late-onset myopathy." (PMID 30791960, 2019). "Here we report that mice lacking Pak1 and Pak2 conditionally in the skeletal muscle lineage develop a late-onset myopathy, characterized by the presence of megaconial mitochondria." (PMID 30791960, 2019).
infectious disease (1 paper, 2017). A disorder directly resulting from the presence and activity of a microbial, viral, or parasitic agent in humans. "In this Box we summarise the available data in regard to PAK2’s role in infectious disease development and progression." (PMID 28430160, 2017). "However, some evidence exists that PAK2 likewise plays an important role in infectious disease establishment in the host tissue." (PMID 28430160, 2017).
kidney disease (1 paper, 2008). "HIV transgenic mice that express nef alleles but lacking the Nef—PAK2 association do not exhibit kidney disease." (PMID 21892329, 2008). "Transgenic mice expressing nef mutants that were able to bind and activate PAK2 failed to exhibit kidney disease." (PMID 21892329, 2008). "Activation of PAK2 alone, however, is not sufficient to develop kidney disease." (PMID 21892329, 2008).
peripheral neuropathies (1 paper, 2024). "Myelin lipids, identified as inhibitors or activators of PAK2, may be utilized to develop therapies for repairing abnormal myelin in peripheral neuropathies." (PMID 38079473, 2024).
PAK2 also shares sentences with these, for which no sentence is quoted: autoimmune disease (3 papers); Chylothorax (2); head and neck squamous cell carcinoma (2); neuroblastoma (2); rheumatoid arthritis (2); Allergy (1); benign tumours (1); bipolar disorder (1); bladder urothelial cancer (1); breast invasive ductal carcinoma (1); Burkitt lymphoma (1); cardiac arrhythmias (1); cardiomyopathies (1); celiac disease (1); cholangiocarcinoma (1); COVID-19 (1); Cushing syndrome (1); cutaneous T-cell lymphoma (1); dermatitis (1); developmental delay (1); diabetic retinopathy (1); enamel hypoplasia (1); epileptic encephalopathies (1); escherichia coli infection (1); fragile X syndrome (1); gastric adenocarcinoma (1); haematopoietic diseases (1); HCMV infection (1); HIV-1 infection (1); Huntington disease (1).
A further 26 diseases each share a sentence with PAK2 in 1 paper.